Y_RNA (Y RNA )
Gene: Miscellaneous RNA gene on chromosome 6 (18,273,165 to 18,273,266, reverse strand). Ensembl gene ENSG00000199715.
Homologues: Orthologues: chimpanzee Y_RNA (99% identical), guinea pig Y_RNA (88% identical), macaque Y_RNA (88% identical). Paralogues in human: RNY3 (86% identical), Y_RNA (86% identical), RNY3P1 (85% identical), Y_RNA (85% identical), Y_RNA (84% identical), Y_RNA (83% identical), RNY3P11 (82% identical), Y_RNA (82% identical), RNY3P5 (81% identical), Y_RNA (81% identical), RNY3P10 (80% identical), RNY3P7 (80% identical), and 93 more.